ABCC1 (ATP binding cassette subfamily C member 1 (ABCC1 blood group))
Diseases named in the same sentence as ABCC1 in open-access papers (continued):
Sharing a sentence is not in itself a finding about the gene and the disease.
endometrial cancer (2 papers, 2021 to 2024). Primary or metastatic malignant neoplasm involving the endometrium (mucous membrane that lines the endometrial cavity). "We performed a comprehensive analysis of mutations present in ABCB1, ABCC1, and ABCG2 transporters for endometrial cancer." (PMID 38766631, 2024).
endothelial dysfunction (2 papers, 2017 to 2021). In vascular diseases, endothelial dysfunction is a systemic pathological state of the endothelium (the inner lining of blood vessels) and can be broadly defined as an imbalance between vasodilating and vasoconstricting substances produced by (or acting on) the endothelium. "In this study, the ABCC1 inhibitor MK571 significantly improved endothelial dysfunction and reduced atherosclerotic lesion formation in the apolipoprotein E (ApoE) knockout mouse model of atherosclerosis." (PMID 28383515, 2017).
gallbladder cancer (2 papers, 2019 to 2020). "Evidence has indicated that overexpression of miR-145 sensitizes gallbladder cancer cell lines to cisplatin by increased ABCC1 expression." (PMID 33081171, 2020). "Low levels of ABCC1 in gallbladder cancer predicts poor prognosis of patients who received chemotherapy." (PMID 33081171, 2020). "More recently, miR-145 was shown to regulate cisplatin resistance in gallbladder cancer cell lines by targeting ABCC1." (PMID 35582590, 2019). "Lower miR-145 and higher ABCC1 expression levels in gallbladder tissue predicted poor prognosis of gallbladder cancer patients who received chemotherapy." (PMID 35582590, 2019).
hemochromatosis (2 papers, 2021 to 2024). A disorder of iron metabolism characterized by a triad of HEMOSIDEROSIS; LIVER CIRRHOSIS; and DIABETES MELLITUS. "ABCC1 has an important role in maintaining cellular redox status also in placental cells, GCLM is the rate-limiting enzyme in the synthesis of the major cellular anti-oxidant GSH, and HFE malfunction is associated with systemic iron overload (hemochromatosis) promoting oxidative stress." (PMID 34220941, 2021). "Seven GMs, including ABCC1, ADRB2, EDNRA, hemochromatosis (HFE), HLA, interleukin 8 (IL-8), TCF7L2, and SLC11A1, had two studies conducted." (PMID 40225935, 2024).
Hypercholesterolemia (2 papers, 2017 to 2022). An increased concentration of cholesterol in the blood. "However, we concluded that in a low dose of atorvastatin, ABCB1 and ABCC1 polymorphisms may have an effective impact on atorvastatin efficacy in reduction of LDL-C serum level in Iranian patients with primary hypercholesterolemia." (PMID 27238935, 2017).
neuropathies (2 papers, 2021 to 2022). "CEP72 rs924607 is associated with neuropathies, and ADME analyses show associations between neuropathies and ABCC1 rs3784867, and SLC5A7 rs1013940." (PMID 34948113, 2021).
oral cancer (2 papers, 2024 to 2025). "In one of these studies, high expression of ABCC1 was associated with poor prognosis in patients with oral carcinoma treated with radiotherapy and chemotherapy, suggesting that ABCC1 expression might be clinically relevant." (PMID 39201428, 2024). "ABCC1, also known as MRP1, has been involved in drug elimination in various tissues of the body, including oral cancer, like ABCB1." (PMID 40362545, 2025).
psoriasis (2 papers, 2013 to 2023). An autoimmune condition characterized by red, well-delineated plaques with silvery scales that are usually on the extensor surfaces and scalp. "Genetic polymorphisms in ABCC1 (rs35592 T>C; rs246240 A>G, rs2238476 G>A) have been associated with response to and toxicity from MTX in psoriasis patients." (PMID 37761008, 2023).
sarcoma (2 papers, 2007 to 2022). A usually aggressive malignant neoplasm of the soft tissue or bone. "Lower levels of sarcoma CSC markers SOX2, NANOG, ALDH1A1, ABCB1 and ABCC1 were observed in silenced cells in 2D and in CSC-enriched cultures (single-cell and 3D/spheroid)." (PMID 35864381, 2022). "Besides, CSC and drug-resistance related genes in sarcoma such as SOX2, NANOG, ALDH1A1, ABCB1 and ABCC1 were down-regulated in 2D, as well as in CSC-enriched cultures (colony-forming and 3D/ spheroid)." (PMID 35864381, 2022).
serous ovarian cancer (2 papers, 2017 to 2023). "The ATP-binding cassette transporter (ABCC1) is associated with poor survival and chemotherapy drug resistance in high grade serous ovarian cancer (HGSOC)." (PMID 37838788, 2023). "Among the SLC22 and ABC genes, SLC22A7 and ABCC1 were amplified in 3.5 and 2.5% of patients, respectively, with serous ovarian cancers." (PMID 28674494, 2017). "For example, overexpression of ABCC1 and ABCG2 in serous ovarian cancer reduces the cellular accumulation of anticancer drugs, and this leads to the development of MDR and poor prognosis." (PMID 28674494, 2017).
thyroid carcinoma (2 papers, 2014 to 2017). "S1P is exported from mast cells via ABCC1, from astrocytes via ABCA1, from endothelial cells via ABCA1 and ABCC1, and from thyroid carcinoma cells via ABCC1." (PMID 28912626, 2017). "S1P has been shown to be exported from mast cells via ABCC1 (also known as multidrug resistant protein 1; MRP1), from astrocytes via ABCA1, from endothelial cells via ABCA1 and ABCC1, and from thyroid carcinoma cells via ABCC1." (PMID 25133174, 2014).
acute leukemia (1 paper, 2022). A clonal (malignant) hematopoietic disorder with an acute onset, affecting the bone marrow and the peripheral blood. "A small cohort performed in an Arab population correlated the expression of 4 ABCC1 SNPs with a lower CR, drug sensitivity and relapsed/refractory disease in acute leukemia." (PMID 35456712, 2022).
Arrhythmia (1 paper, 2021). Any cardiac rhythm other than the normal sinus rhythm. "Specific inhibitors of other dox transporters (ABCB1, ABCC1) are known to cause cardiotoxicity manifested as QT prolongation and arrhythmias." (PMID 34944997, 2021).
asthenia (1 paper, 2023). Clinical sign or symptom manifested as debility, or lack or loss of strength and energy. "As for the emergence of asthenia, patients carrying the ABCC1 rs2238476-AG genotype showed a higher risk of having this adverse event during therapy with MTX (OR = 4.70, 95% CI = 1.23–19.87, p = 0.026)." (PMID 37761008, 2023). "The toxicity analysis by subtypes showed that the ABCC1 rs2238476-AG genotype (AG vs. GG: OR = 8.10; 95% CI = 1.69–46.63; p = 0.011) and FOXP3 rs376154-GT genotype (OR = 4.11; 95% CI = 1.22–15.30; p = 0.027) were associated with the appearance of asthenia." (PMID 37761008, 2023).
basal cell carcinoma (1 paper, 2024). A carcinoma involving the basal cells. "By analyzing probes matching ABCC1 mRNA in a GEO microarray dataset including 15 basal cell carcinoma (BCC) and 11 cSCC tissue samples, we observed a significant increase in ABCC1 expression in both BCC and cSCCs." (PMID 39201428, 2024). "Based on the observation that ABCC1 expression might be linked to the aberrant proliferation of keratinocytes, we analyzed ABCC1 expression in basal cell carcinoma (BCC) and cutaneous SCC (cSCC), two skin diseases characterized by keratinocyte hyper-proliferation." (PMID 39201428, 2024).
cancers of the kidney (1 paper, 2010). "ABCC1 has been associated with chemotherapeutic resistance in several types of cancer, including cancers of the kidney, breast, and prostate." (PMID 20707922, 2010).
colitis (1 paper, 2023). Inflammation of the colon. "ABCC1 has been implicated as a protectant against methotrexate’s toxicity in the intestine after an ABCC1−/− mouse model of colitis found that the disease was associated with higher mortality and severe epithelia damage." (PMID 37438132, 2023).
colorectal adenocarcinoma (1 paper, 2025). The most common type of colorectal carcinoma. "Furthermore, low circ-ABCC1 expression was associated with tumor growth and disease progression, while the overexpression of circ-PRMT1 in colorectal adenocarcinoma has very recently been shown to predict recurrence and poor OS, similarly to circ-CCT3." (PMID 41153715, 2025).
embryonal rhabdomyosarcoma (1 paper, 2022). A poorly circumscribed morphologic variant of rhabdomyosarcoma. "In cases of embryonal rhabdomyosarcoma ABCC1 expression correlated with poor survival." (PMID 35328603, 2022).
head and neck squamous cell carcinoma (1 paper, 2021). A squamous cell carcinoma that arises from any of the following anatomic sites: lip and oral cavity, nasal cavity, paranasal sinuses, pharynx, larynx, and salivary glands. "In patients with head and neck squamous cell carcinoma, high expressions of ABCB1 and ABCC1 were associated with favorable survival." (PMID 33531973, 2021).
hypopharyngeal carcinoma (1 paper, 2023). Carcinoma, predominantly squamous cell, arising from the epithelial cells of the hypopharynx. "However, only four genes have been reported to inhibit the chemosensitivity in HSCC or hypopharyngeal carcinoma, including PTGS2, PHF20, ABCC1, and MCL1." (PMID 37791141, 2023).
internalizing disorder (1 paper, 2025). A type of mental or behavioral disorder, typically in children and young adults, with symptoms including depression, anxiety and withdrawal. "Our study provides insights into the genetic mechanisms of childhood internalizing disorders in an admixed Latin American population, with a particular focus on variants in the ABCC1 gene and associated neurobiological pathways." (PMID 39858610, 2025). "Although direct links between ABCC1 and internalizing disorders are not well established, this protein is known to regulate corticosterone levels, which, similar to cortisol, influence stress-related outcomes." (PMID 39858610, 2025).
leukopenia (1 paper, 2024). "In multivariate analysis risk, symptoms of overall leukopenia were conditioned by two genetic factors: ABCC1 gene rs129081 allele G (OR 1.89; 0.27–0.99; p = 0.048) and DPYD rs291593 allele T (OR 1.73; 1.08–2.76; p = 0.020)." (PMID 39596349, 2024).
lymph node metastasis (1 paper, 2015). "Correlation analysis showed that MRP1/ABCC1 expression was significantly associated with the SCLC patient’s clinical stage and chemotherapy response, but not with gender, smoking, age or lymph node metastasis." (PMID 25880778, 2015).
metabolic syndrome (1 paper, 2018). A cluster of metabolic risk factors for CARDIOVASCULAR DISEASES and TYPE 2 DIABETES MELLITUS. "Finally, another protein coding gene, ABCC1, which contains haplotype block 8, is also noteworthy, as it also appears to be pertinent to metabolic syndrome." (PMID 30263052, 2018).
metastatic tumors (1 paper, 2023). "More investigations must be undertaken in order to evaluate the real benefits that the gained from the upregulation of ABCB1 and ABCC1 on invasiveness and aggressiveness of metastatic tumors." (PMID 37047018, 2023).
mucositis (1 paper, 2024). Mucositis is inflammation and damage of the mucous membranes lining the mouth and other parts of the gastrointestinal (GI) tract. "Additional studies have found a relationship between mucositis and SNPs in non-coding RNA pathways, in genes encoding ghrelin, in the ABCC1 gene pathway, and in autophagy-related genes." (PMID 38473311, 2024).
multiple sclerosis (1 paper, 2023). A progressive autoimmune disorder affecting the central nervous system resulting in demyelination. "The discovered effects of ABCC1 also have implications for DMF treatment of multiple sclerosis." (PMID 37508364, 2023).
mycoplasma infection (1 paper, 2017). "However, we did not detect any changes in expression or sub-cellular locations of ABCB1, ABCC1 and ABCG2, suggesting that mycoplasma infection alters neither the quantity of ABC transporters nor their functional proportions on cell membrane." (PMID 28976984, 2017).
proteopathies (1 paper, 2012). "Furthermore, we chose ABCC1- (MRP1, subfamily C) deficient mice because little information is available about its function in neurogenic processes, and because we recently showed its potential significance for brain homeostasis in proteopathies such as Alzheimer's disease." (PMID 22545122, 2012).
rectal cancer (1 paper, 2022). A primary or metastatic malignant neoplasm that affects the rectum. "The survival analysis of ABCA5, ABCA8, and ABCC1 genes was performed in the TCGA colon and rectal cancer (TCGA-COADREAD) and GSE24551-GPL5175 datasets." (PMID 35783152, 2022).
retinoblastoma (1 paper, 2016). A malignant tumor that originates in the nuclear layer of the retina. "Our results showed that single exposure to chemotherapy or even longer and continuous treatments with melphalan or topotecan at the IC50 did not alter ABCB1, ABCC1, or ABCG2 expression levels in retinoblastoma and HUVEC cells." (PMID 27467588, 2016).
Sepsis (1 paper, 2026). Sepsis is defined as life-threatening organ dysfunction caused by a dysregulated host response to infection. "The observed low expression of ABCC1 in sepsis is strongly associated with mitochondrial damage mechanisms." (PMID 41509654, 2026). "Using machine learning algorithms, we identified three key diagnostic genes for sepsis (ABCC1, CYP1B1, and PPARG) with high reliability and broad applicability." (PMID 41509654, 2026). "ROC curve analysis was performed to evaluate the diagnostic value of ABCC1, CYP1B1, and PPARG in sepsis patients." (PMID 41509654, 2026). "Among sepsis patients, ABCC1 was identified as a low-expression gene, while CYP1B1 and PPARG were identified as high-expression genes." (PMID 41509654, 2026). "Single-cell analysis further revealed that ABCC1, CYP1B1, and PPARG are highly expressed in monocytes, which are central to the immunopathology of sepsis, acting as key mediators of both inflammation and immune suppression." (PMID 41509654, 2026). "The results demonstrated that ABCC1 was significantly downregulated, while CYP1B1 and PPARG were significantly upregulated in the sepsis organoids." (PMID 41509654, 2026). "Additionally, three key genes (ABCC1, CYP1B1, and PPARG) were identified based on Prevotella 9, fatty acids, and PANoptosis, contributing to sepsis progression via the regulation of neutrophils, oxidative stress, and macrophage polarization." (PMID 41509654, 2026). "Additionally, the predominant expression of ABCC1, CYP1B1, and PPARG in monocytes underscores the critical role of monocyte functional reprogramming in sepsis pathogenesis." (PMID 41509654, 2026).
sickle cell disease (1 paper, 2022). Sickle cell anemias are chronic hemolytic diseases that may induce three types of acute accidents: severe anemia, severe bacterial infections, and ischemic vasoocclusive accidents (VOA) caused by sickle-shaped red blood cells obstructing small blood vessels and capillaries. "Bantu, Afro-related ethnolinguistic cultural groups, and Latin America have a similar low proportion of pathogenic variants in most of the sickle cell disease-specific genes, except in MY O 7B, CPS1, COL6A3, MTRR, SLC22A5, ABCC1, and RPL3L." (PMID 35812734, 2022).
skin cancer (1 paper, 2013). "Meanwhile, the level of ABCC1 in skin cancer subjects was eightfold to 26-fold lower than the levels in normal subjects." (PMID 25505559, 2013). "Interestingly, we found that the mRNA expression levels of ABCC1 in skin RNA from skin cancer patients were significantly lower compared to the levels in normal subjects." (PMID 25505559, 2013).
synovial sarcoma (1 paper, 2022). "In synovial sarcomas we demonstrated positive correlation of ABCC1 expression with SI (Ifo) and SI (Dox + Ifo) as well as ABCG2 expression gene with SI (Doс)." (PMID 35328603, 2022).
T-cell lymphomas (1 paper, 2015). "It was found that there were significant differences in ABC-transporter expression between B- and T-cell lymphomas, with T-cell lymphomas showing a higher ABCB5 and ABCC5, and lower ABCC1 expression compared to B-cell lymphomas." (PMID 29061939, 2015).
uterine corpus endometrial carcinoma (1 paper, 2024). A endometrial carcinoma (disease) that involves the body of uterus. "Out of these, mutations observed in uterine corpus endometrial carcinoma were taken into account for further analysis, which narrowed down to a total of 248 mutations: 118 in ABCB1, 82 in ABCC1, and 48 in ABCG2." (PMID 38766631, 2024).
vascular tumor (1 paper, 2024). "IHC scores of CXCL1、CXCL2、IL6、ABCC1、LRP、BCL2, vascular tumor thrombus, ascites cancer cells, maximum tumor diameter, neoadjuvant chemotherapy, and HE4 were included in the prediction model." (PMID 38509620, 2024). "As predictors, the immunohistochemical scores of CXLC1, CXCL2, IL6, ABCC1, LRP, BCL2, vascular tumor thrombus, ascites cancer cells, maximum tumor diameter, neoadjuvant chemotherapy, and HE4 were employed." (PMID 38509620, 2024). "Finally, the immunohistochemical scores of CXLC1, CXCL2, IL6, ABCC1, LRP, BCL2, vascular tumor thrombus, ascites cancer cells, maximum tumor diameter, neoadjuvant chemotherapy, and HE4 were employed." (PMID 38509620, 2024).
Wilms tumor (1 paper, 2023). An embryonal neoplasm characterized by the presence of epithelial, mesenchymal, and blastema components. "Previous reports showed that ABCB4 and ABCC1 overexpression correlates with high-risk and significantly shorter disease-free survival time in patients with Wilms tumors (WT)." (PMID 36901890, 2023).